SMAD3 (SMAD family member 3)
Diseases named in the same sentence as SMAD3 in open-access papers (continued):
Sharing a sentence is not in itself a finding about the gene and the disease.
osteoarthritis (continued). "CHST3, SMAD3, and GDF5 accrued the highest levels of confidence, each with 6 different lines of evidence in support of their involvement in osteoarthritis." (PMID 34450027, 2021). "We found strong evidence for co-localisation of five osteoarthritis signals with cartilage molQTLs for ALDH1A2, NPC1, SMAD3, FAM53A and SLC44A2." (PMID 33637762, 2021). "In this context, we hypothesize that a key factor contributing to joint osteoarthritis-like changes could be the diminished secretion of SAM in the synovium, leading to the activation of the TGF-β1-stimulated Smad3/4 signaling pathway." (PMID 38994346, 2024). "Nevertheless, this score is varying from 0 to 8, illustrating the high clinical variability of SRD and therefore the lack of power of such a score to detect SMAD3 pathogenic variants as it was designed for MFS and does not include premature osteoarthritis which is more frequent and specific of SRD." (PMID 32154675, 2020). "Its overexpression induces suppression of SMAD3, resulting in inhibition of cell proliferation, migration, and invasion in osteosarcoma cells, and in downregulation of COL2A1 and Aggrecan and upregulation of ADAMTS in chondrocytes, which may be involved in the development of osteoarthritis." (PMID 35401675, 2022). "Several osteoarthritis GWAS signals were found to co-localise with eQTLs in only 1 or 2 of 53 tissues (e.g. ALDH1A2: ovary and tibial artery, SMAD3: skeletal muscle; SLC44A2: adrenal gland), without clear transferability of results to disease-relevant tissue." (PMID 33637762, 2021).
pancreatic cancer (47 papers, 2012 to 2026). "The aggressive natures of pancreatic tumors are associated with the deactivation of stromal PSCs induced by CSF1 as well as with the mesenchymal nature of PDAC cells induced by SMAD3." (PMID 36038612, 2022). "Moreover, the levels of p-Smad3 and nuclear β-catenin were inversely associated with overall survival in pancreatic cancer." (PMID 28287611, 2017). "Therefore, we assume that FZD7 plays a role through the canonical WNT pathway, and that the TGF-β/SMAD3 pathway could be associated with the regulation of the FZD7/β-catenin pathway in the malignant biological behavior of pancreatic cancer cells." (PMID 35854234, 2022). "Mechanistically, they demonstrated that pancreatic cancer cell-derived TGF-β activates SMAD3 signaling in CAFs." (PMID 41439136, 2026). "Treatment with atorvastatin or NSDHL knockout activates SREBP1, which promotes TGF-β1 expression and induces a canonical Smad2 and Smad3 effector cascade, resulting in the induction of epithelial-mesenchymal transition in pancreatic cancer." (PMID 39516821, 2024). "The enhancer targeting miR-492 activates NR2C1 expression and further enhances EMT in pancreatic cancer via the TGF-β/Smad3 pathway." (PMID 38943031, 2024). "Further, KLF11 associates with SMAD3 and enhances TGF-β-induced growth inhibition by repressing SMAD7 and Myc expression in epithelial and pancreatic cancer cells." (PMID 38543112, 2024). "Further, TGFβ1 was recently shown to induce a novel complex composed of NFAT5, Smad3, and Smad4, which promotes epithelial-to-mesenchymal transition in pancreatic cancer cells." (PMID 39595620, 2024). "Numerous transcription factors have been identified as regulating pancreatic cancer growth, including SMAD3 and TWIST1, among others." (PMID 36090038, 2022). "In contrast, galangin inhibited TGFβ/Smad signaling as well as inactivated Smad3 resulting in growth inhibition in prostate and pancreatic cancer cells." (PMID 34890367, 2021). "Upon silencing of TAp73 in a cell line derived from these mice, both Bgn and Smad3 were downregulated, suggesting the exciting possibility that Rac1b is targeted by TAp73 to participate in its tumor-suppressive function in pancreatic cancer." (PMID 31817656, 2019). "In human pancreatic cancer Panc-1 cells, results from knockdown of TGFβ signaling mediators Smad2 and Smad3 demonstrated an opposite function of Smad2 versus Smad3 on TGFβ-induced cell migration." (PMID 29379802, 2017). "The involvement of the Smad3/TGFβ signaling pathway during pancreatic tumor progression was confirmed by real-time PCR, showing a significant increase (P<0.005) in mCherry mRNA levels in Tg(ptf1a:Gal4)/UAS:eGFP-KRASG12D compared with the control." (PMID 24878567, 2014). "Naringenin (Nar) down-regulated EMT markers expression in both mRNA and protein levels by inhibiting TGF-β1/Smad3 signal pathway in the pancreatic cancer cells." (PMID 23300530, 2012). "Among the interaction partners of the markers, more than one-third has been previously reported as associated with survival or prognosis in pancreatic cancer, including PPARG, MUC4, and SMAD3." (PMID 22615549, 2012). "In conclusion, Nar suppresses the migration, invasion and Gem resistance of pancreatic cancer cells by inhibiting TGF-β/Smad3-mediated EMT." (PMID 23300530, 2012). "We previously showed that TGF-β1 is a key regulator of MUC4 expression in pancreatic cancer cells via the TGF-βRII/Smad3–4 pathway." (PMID 22393391, 2012). "A previous study demonstrated that Smad3 and Smad7 expression exhibits circadian rhythms in pancreatic cancer cells and zebrafish, suggesting that their expression may be regulated by intrinsic circadian clock mechanisms." (PMID 41257391, 2026).
pancreatic cancer (continued). "A report demonstrated that SMAD3 facilitates tumor growth in pancreatic cancer." (PMID 34439202, 2021). "Results showed that purified recombinant human FST (30-317 aa) protein significantly inhibited activin A-induced Smad3 phosphorylation, decreased gemcitabine resistance and reduced gene expressions of pancreatic cancer stemness markers in gemcitabine resistant PDAC cells." (PMID 33537082, 2021). "To explore whether SMAD2 or SMAD3 is responsible for the PNI of pancreatic cancer, we designed siRNA to knockdown SMAD2 and SAMD3 in PANC-1 cell line respectively." (PMID 34671554, 2021). "SAMD2 and SMAD3 are both responsible for the PNI of pancreatic cancer." (PMID 34671554, 2021). "It remains to be seen whether RAC1B (over)expression in pancreatic tumors correlates positively with SMAD3 expression in vivo." (PMID 31817656, 2019). "In sum, this study has identified SMAD3 and BGN as novel RAC1B target genes in pancreatic cancer cells with SMAD3, in an activation-independent manner, inducing BGN, which subsequently executes inhibition of cell motility in TGF-β-dependent and/or independent fashion." (PMID 31817656, 2019). "In corroboration, a previous report demonstrated that in pancreatic cancer TGFβ induced nuclear translocation of NFAT-1 that displaced Smad3 repressor complexes from the c-Myc promoter resulting in transcription and a switch from cell cycle inhibitor to growth promoter activities." (PMID 25918253, 2015). "Here, we try to address whether Nar exerts its anti-metastatic and anti-resistant effects on pancreatic tumor cells by preventing tumor cells EMT through down regulating TGF-β/Smad3 signaling pathway." (PMID 23300530, 2012). "However, only miR-103 was directly involved in the regulation of pancreatic cancer-associated processes: E-cadherin signalling events (CDH1), TGF beta signalling pathway (TGFBR2, APC, CDH1, CREBBP, EP300, SMAD3, TSC2), and altered TFG-beta SMAD dependent signalling (TGFBR2, SMAD3, and FBXW7)." (PMID 29285254, 2017). "However a previous report demonstrated that in pancreatic cancer TGFβ induces nuclear translocation of NFAT-1 that displaces Smad3 repressor complexes from the c-Myc promoter resulting in transcription and a switch from cell cycle inhibitor to growth promoter activities." (PMID 25918253, 2015). "Meanwhile, the protein expression levels of SMAD2, SMAD3, SMAD4, and p-SMAD2/3 were also detected in the pancreatic cancer cells with the ITGA2 gene silenced." (PMID 35193647, 2022). "However, it is unclear whether SAMD2 or SMAD3 is responsible for the PNI of pancreatic cancer." (PMID 34671554, 2021). "In pancreatic cancer cells, NFAT2 is responsible for the displacement of the SMAD family member 3 (Smad3) repressor from the c-Myc gene promoter, leading to the activation of c-Myc transcription." (PMID 32397368, 2020). "The most significantly identified enriched pathway were about the pancreatic cancer (P = 0.0011), which four target genes (CDC42, MAPK1, SMAD3, and CDK6) were predicted to be involved in." (PMID 33178707, 2020). "In pancreatic cancer cells, our study showed that silencing of Cbl-b expression inhibited proliferation in PDAC cells by up-regulation of the Smad3/p21 signaling." (PMID 27494897, 2016). "For example, circEIF3I may act as a molecular scaffold, interacting with SMAD3 and AP2A1 to form a complex that facilitates SMAD3 transport to early endosomes, activating downstream TGF-β signaling and promoting pancreatic cancer progression." (PMID 38802795, 2024).
pancreatic cancer (continued). "In epithelioid pancreatic cancer cells, AKT phosphorylation might enhance the activity of SMAD3 and stimulate SMAD-mediated cell proliferation." (PMID 38543112, 2024). "High FZD7 expression in pancreatic cancer can accelerates hepatic metastases by promoting EMT and strengthening cell stemness, and FZD7 can work through the canonical Wingless-type (WNT) signaling pathway and participate in TGF-β/SMAD3 signaling pathway also." (PMID 35854234, 2022). "Furthermore, Smad3's β4 region-dependent downregulation of ARHGAP24 and ARHGAP27 was also observed in PANC-1 human pancreatic cancer cells." (PMID 33741342, 2021). "The data of this study report on an unexpected role of (non-C-terminally phosphorylated) SMAD3 in transducing an antimigratory signal derived from RAC1B in pancreatic carcinoma cells." (PMID 31817656, 2019). "We also observed that SMAD3, a negative prognostic factor for pancreatic cancer patients and gene that promotes epithelial-mesenchymal transition was also decreased after HOTTIP knockdown." (PMID 25912306, 2015). "Targeting this TGF-β/SMAD3/ATF4 axis or directly inhibiting CBS effectively suppressed cysteine secretion, reversed ferroptosis resistance, and sensitized PDAC to chemotherapy in vitro and in vivo, offering novel therapeutic strategies for treating pancreatic cancer." (PMID 41439136, 2026). "Although there are scientific reports on the prognostic values of SMAD3 and CTNNB1 in pancreatic cancer, the precise functions of Jun Oncogene (JUN) and TCF-7 in the pathogenesis of pancreatic cancer are still largely unknown and require further understanding and research." (PMID 33194391, 2020). "Furthermore, the overexpression of ITGA2 could significantly inhibit the mRNA level of SMAD2 in pancreatic cancer cells, but not those of the SMAD3 or SMAD4." (PMID 35193647, 2022). "Among the five TFs identified, activation of SMAD3 and inhibition of SMAD7 may together indicate a possible activation of TGF-beta signaling, which is known to play a dual role as both pro-tumorigenic and tumor-suppressive in pancreatic cancer, depending on tumor stage and microenvironment." (PMID 33194391, 2020).
myocardial infarction (43 papers, 2015 to 2026). Gross necrosis of the myocardium, as a result of interruption of the blood supply to the area, as in coronary thrombosis. "Mice with Smad3 global deficiency had reduced collagen deposition and inflammatory infiltration after myocardial infarction." (PMID 35461308, 2022). "In cardiovascular diseases, Smad3 is pathogenic as deletion of Smad3 protects against cardiovascular inflammation and fibrosis under various pathological conditions such as hypertension, myocardial infarction and obese diabetes." (PMID 33733577, 2021). "SMAD3-deficient fibroblasts exhibit reduced migratory potential, and reduced potential for transdifferentiation, that is consistent with a reduction in α-smooth muscle actin expressing myofibroblasts with reduced contractile function in SMAD3-deficient hearts after myocardial infarction." (PMID 25788886, 2015). "It has been demonstrated that the the Notch signal inhibits thetransformation of CMT by antagonizingthe TGF-β1/Smad3 signal transduction, suppressing myocardial fibrosisafter myocardial infarction." (PMID 40160574, 2025). "In a myocardial infarction (MI) model, deletion of Smad3 in cardiomyocytes protects against MI by suppressing apoptosis and attenuating adverse remodeling, whereas its deletion in fibroblasts or macrophages promotes MI pathogenesis." (PMID 38569937, 2024). "Suppression of Pick1 in macrophages potentiates Smad3 signalling and enhances efferocytosis, minimizing heart necrosis in rats with myocardial infarction." (PMID 38865332, 2024). "Furthermore, cardiac remodeling induced by myocardial infarction (MI) and diabetes mellitus are attenuated by the loss of SMAD3 in mice." (PMID 35185581, 2022). "A previous study suggested that miR-24 can improve heart function and attenuate fibrosis after myocardial infarction by reducing Smad3 phosphorylation." (PMID 30820195, 2019). "Of note, a recent study reveals that myofibroblast- and cardiomyocyte-specific activation of SMAD3 has contrasting functional outcomes in healing myocardial infarction." (PMID 31915683, 2019). "All these parameters indicate a strong impact of TGFβ/SMAD3 on fibrosis in post-myocardial infarction." (PMID 25788886, 2015). "Additionally, miR-96 promotes myocardial infarction-induced cardiac fibrosis through the Smad7/Smad3 pathway." (PMID 41154662, 2025). "Moreover, IMD contributes to decreased atrial fibrosis in rats after myocardial infarction operation through the TGF-β1/Smad3 signaling pathway." (PMID 37745233, 2023). "These two molecules are downstream factors of Smad3 in myocardial infarction." (PMID 34904361, 2022). "The activation of activin receptor-like kinase 4 (ALK4) signaling plays a pivotal role in the pressure-overloaded heart, and haplodeficiency of ALK4 can alleviate cardiac fibrosis secondary to myocardial infarction and preserve cardiac function through partially inactivating the Smad3/4 pathway." (PMID 35402148, 2022). "Also, cardiomyocyte-specific Smad3 deletion can attenuate hypertrophic remodeling and systolic dysfunction in a mouse model of myocardial infarction." (PMID 36269647, 2022). "TGF-β could activate Smad3 in macrophages, and the TGF-β/Smad3 activation exerted protective effects by stimulating phagocytosis of macrophages in myocardial infarction." (PMID 35784347, 2022). "Moreover, TGF-β1 is overexpressed in the heart in a high-cholesterol-fed porcine model of myocardial infarction, and its downstream Smad2 and Smad3 are activated, thereby increasing collagen synthesis and the levels of Col1a1, Col3a1, and α-SMA." (PMID 34485393, 2021). "Western blot showed that QSG could down-regulate expressions of TGF-β1 and Smad3 in the border zone of myocardial infarction." (PMID 31824322, 2019). "A study on rats indicated that quercetin downregulated TGF‐β1 and SMAD3 and suppressed the phosphorylation of SMAD3 in both control and myocardial infarction (MI)‐induced rats." (PMID 41195524, 2025).
myocardial infarction (continued). "Although TGF-β activates both Smad2 and Smad3 in vivo, CF-specific Smad2/3 knockout mice demonstrated that the observed effects on cardiac fibrosis and scar formation following pressure overload or myocardial infarction, respectively, were mainly attributed to Smad3." (PMID 35626694, 2022). "Involvement of Smad3 in upregulated inflammatory responses has been supported by several recent studies using such diverse models as ischemic nephropathy, hypertensive renal and cardiac remodeling, healing myocardial infarct, and orthotopic heart transplant rejection." (PMID 36269647, 2022). "TGF-β1levels increase significantly during myocardial infarction and promote myocardialfibrosis through the TGF-β1/Smad3 signaling pathway." (PMID 40160574, 2025). "In rats after myocardial infarction operation, IMD improved atrial fibrosis and reduced the inducibility of atrial fibrillation through the TGF-β1/Smad3 and TGF-β1/Nox4 pathways." (PMID 37745233, 2023). "The activation of Smad3 in turn accelerates milk-fat globule EGF factor-8 (MFGE8) synthesis, which initiates anti-inflammatory cascades, contributes to the anti-inflammatory phenotype of macrophages, and ultimately protects the heart from myocardial infarction." (PMID 35461308, 2022). "For example, SMAD3 activation in murine myofibroblasts played a protective role in cardiac injury by maintaining ECM network, whereas SMAD3 signaling in cardiomyocytes promoted cardiomyocyte death and exacerbated systolic dysfunction after myocardial infarction (MI)." (PMID 34081224, 2021).